NOS3 (nitric oxide synthase 3)
Diseases named in the same sentence as NOS3 in open-access papers (continued):
Sharing a sentence is not in itself a finding about the gene and the disease.
preeclampsia (continued). "Genotype and allele frequencies for NOS3 and GUCY1A3 polymorphisms in normotensive pregnant women and in patients with gestational hypertension and preeclampsia." (PMID 38469120, 2024). "MDR interaction models among NOS3 and GUCY1A3 polymorphisms in normotensive pregnant (NP) compared with both gestational hypertension (GH) and with preeclampsia (PE)." (PMID 38469120, 2024). "Seven alleles were significantly or marginally significantly associated with preeclampsia, which involved six genes (rs4762 in AGT, rs1800896 in IL-10, rs1800629 and rs1799724 in TNFα, rs2070744 in NOS3, rs7412 in APOE, and rs2549782 in ERAP2)." (PMID 30112393, 2018). "Finally, due to missing information about disease status (e.g., early or late onset; mild or severe disease status), we cannot further explore the associations between NOS3 polymorphisms and preeclampsia risk by disease status, and this may also have influenced the interpretation." (PMID 26997284, 2016). "In this meta-analysis, we examined the associations between the three NOS3 gene polymorphisms (G894T, T-786C, and VNTR 4b/a) and the preeclampsia risk." (PMID 26997284, 2016). "We compared the distribution of genotypes for NOS3 G894T, T-786C, and VNTR in intron 4, as well as MMP2 C-1306T and MMP9 C-1562T, and tested their association with preeclampsia and its major complications." (PMID 26317342, 2015). "The endothelial nitric oxide synthase gene (NOS3) has been proposed as a candidate gene for preeclampsia." (PMID 22051068, 2011). "Similarly, NOS3 T(-786)C and NOS3 27-bp VNTR 4b/a genetic polymorphisms were associated with the risk of developing preeclampsia." (PMID 40142738, 2025). "During the occurrence of preeclampsia, plasma exosomal miR-155 derived from the placenta can be internalized by endothelial cells, thereby inhibiting NOS3 expression in the vascular endothelium, reducing NO production, and consequently affecting the progression of preeclampsia." (PMID 38802855, 2024). "Interestingly, the contribution of sENG to vascular pathology in preeclampsia is partially due to effects on NOS3; in concert with FLT1, ENG reduces placental angiogenesis and vasodilation of maternal spiral arteries, and increases vessel permeability." (PMID 37012406, 2023). "In conclusion, this meta-analysis demonstrates that G894T and T-786C polymorphisms, but not VNTR 4b/a, in the NOS3 gene are associated with an increased risk of preeclampsia." (PMID 26997284, 2016). "Finally, 41case-control studies, including 5,211 cases and 8,779 controls, were used to evaluate the associations of NOS3 polymorphisms (G894T, T-786C, and VNTR 4b/a) with the risk for preeclampsia." (PMID 26997284, 2016). "Given the limitations of the candidate-gene approach in investigating complex traits, the evidence of our study does not support the major contributory role of these common NOS3 variants in preeclampsia." (PMID 22051068, 2011). "Notably, polymorphisms and haplotypes of NOS3 gene were associated with the disease or with the responsive and non-responsive subgroups of patients with preeclampsia." (PMID 29541029, 2018). "The most relevant targets for preeclampsia were: AR, VDR, SLC6A2, NOS3 and CHRM4, while ABCG2, ERBB2, CES1 and REN led to the most relevant off-targets." (PMID 33546161, 2021). "The analysis of the final models points toward a relevance of AR, VDR, SLC6A2, NOS3 and CHRM4 as targets for preeclampsia." (PMID 33546161, 2021). "Given that uteroplacental miR-29b and miR-21 were upregulated in preeclampsia and IUGR, it is probably that NOS3, CTH and KCNMB1 in uteroplacental vessels are also targeted directly or indirectly by these miRNAs." (PMID 31671866, 2019). "We detected a higher frequency of the presence of SNPs in the NOS3 gene in the group of pregnant women with preeclampsia, but not in the MMP2 and MMP9 genes." (PMID 26317342, 2015). "Thus, individual NOS3 genotypes might not be reliable markers of risk for developing preeclampsia." (PMID 22051068, 2011).
preeclampsia (continued). "Therefore, the endothelial nitric oxide synthase gene (NOS3), located at the 7q35-q36 region, has emerged as a logical candidate gene in the development of preeclampsia." (PMID 22051068, 2011).
Insulin resistance (42 papers, 2006 to 2025). Increased resistance towards insulin, that is, diminished effectiveness of insulin in reducing blood glucose levels. "Also, a deletion in NOS3, one of the three enzyme isoforms of nitric oxide, causes insulin resistance, glucose intolerance, hyperlipidaemia and hypertension." (PMID 28291256, 2017). "Highlighting a personalized medicine strategy, these medicines ought to be classified according to the NOS3 genotype, metabolic phenotype (e.g., BMI and insulin resistance), and redox status." (PMID 40724818, 2025). "Acly and Nos3 were enriched in the citrate cycle, insulin resistance, and PI3K-Akt signaling pathways." (PMID 37287451, 2023). "While JAK2 and STAT3 were associated with all the noted pathways except insulin resistance and Herpes simplex infection, respectively, only two connections (negative regulation of cell proliferation and insulin resistance) were reported for NOS3." (PMID 33100263, 2020). "NOS3 is associated with anti-obesogenic effects, while NOS2 promotes insulin resistance." (PMID 37371984, 2023). "Many studies recently linked NOS3 gene polymorphisms with an increased risk of migraine, insulin resistance, and T2D; however, the findings were not always conclusive." (PMID 35627115, 2022). "Lastly, the NOS family consists of three members; endothelial NOS (eNOS/NOS3) reported to have an anti-obesogenic effect, the inducible NOS (iNOS/NOS2) that promotes insulin resistance, and the neuronal NOS (nNOS/NOS1) that appears to act as appetite regulator." (PMID 33924357, 2021). "Notably, IL6, NFKBIA, NFKB1, NOS3, PTPN1, PIK3R1, and STAT3 (members in the enriched WGCNA module) have been shown to alter insulin resistance." (PMID 33005175, 2020).
heart failure (30 papers, 2008 to 2025). Inability of the heart to pump blood at an adequate rate to meet tissue metabolic requirements. "In Nos3-deficient mice, smooth muscle cell proliferation in a carotid artery ligation model is suppressed and they display bicuspid aortic valve, heart failure, VSD and ASD." (PMID 30404214, 2018). "The influence of the NOS3 Glu298Asp polymorphism on enzymatic cleavage and thus NO availability has been shown to reduce treatment efficacy in heart failure patients." (PMID 26517550, 2015). "For NOS3 −922 A>G (rs1800779), a higher HR was found in minor allele carriers for heart failure (AA = 1.00, AG+GG = 1.10 (CI = 1.00–1.21), P = 0.046)." (PMID 22470539, 2012). "Minor allele carriers of NOS3 −690 C>T have higher risk of CHD (HR, 1.12; 95% CI, 1.00–1.26) and minor allele carriers of NOS3 −922 A>G have higher risk to heart failure (HR, 1.10; 95% CI, 1.00–1.21 compared to their respective wild-type homozygous individuals." (PMID 22470539, 2012). "In the Genetic Risk Assessment of Heart Failure (GROH) substudy of the African-American Heart Failure Trial, in 786 T/C promoter NOS3 polymorphism, the T allele was associated with LVEF (p = 0.01)." (PMID 28827564, 2017). "The NOS3 is also constitutively expressed in cardiac myocytes, with an enhanced basal production of nitric oxide observed in patients with heart failure." (PMID 23923002, 2013). "Studies on myocardial expression of NOS revealed an upregulation of NOS3 expression in patients with heart failure, an end stage of DCM." (PMID 23923002, 2013). "When minor allele carriers were combined (CT and CC for NOS3 −690 C>T, AG and GG for NOS3 −922 A>G, GT and TT for NOS3 glu298asp G>T), associations were found in the adjusted models between NOS3 −690 C>T and CHD, and NOS3 −922 A>G and heart failure (p<0.05)." (PMID 22470539, 2012). "NO generated by Nos3 plays an important role to maintain vascular homeostasis, and it was reported that the overexpression of Nos3 improved the survival and lung congestion of a heart failure mice model." (PMID 30092100, 2018). "This may have important implications for heart failure patients, where arrhythmias are increased and NOS3 expression is decreased." (PMID 22970362, 2012). "This may have important implication for arrhythmias and sudden cardiac death in heart failure, where NOS3 expression is decreased and β-AR tone is increased." (PMID 22970362, 2012). "Taken together, our data additively show that PDE5A alterations begin at a very early stage in cardiac hypertrophy leading to heart failure, and that the reported increase in PDE5 activity occurs before the loss of its intracellular localization to Z-bands and alteration of NOS3 expression." (PMID 21151982, 2010). "Endothelial NOS (NOS3) plays a critical role in pathological cardiovascular remodeling, including heart failure." (PMID 39456418, 2024).
pulmonary hypertension (30 papers, 2006 to 2025). Increased pressure within the pulmonary circulation due to lung or heart disorder. "NOS3 is essential for neonatal cardiopulmonary transition; eNOS-deficient mice develop impaired alveolarization, pulmonary hypertension, and fatal respiratory distress." (PMID 40941746, 2025). "Initially, immunohistochemical studies showed that pulmonary hypertension was associated with diminished expression of NOS-3." (PMID 16813666, 2006). "We found four genes to be significantly associated with high-altitude pulmonary hypertension (i.e., estimated mPAP ≥ 30 mm Hg) after adjustment for multiple testing: NOS3 rs2070744 (p = 0.003), ARG2 rs3742879 (p = 0.003), DDAH1 rs233122 (p = 0.004), and AGXT2 rs37369 (p = 0.003)." (PMID 34945057, 2021). "While increased DNA hypermethylation leads to suppression of genes (Sod2 and Nos3) encoding vasodilatory proteins and antioxidants in lungs of hypoxic mice, pulmonary artery SMCs of fawn‐hooded rats, and endothelial cells of fetal lamb with pulmonary hypertension." (PMID 35581740, 2022). "SNPs in bone morphogenetic protein receptor 2 (BMPR2) is associated with familial and sporadic pulmonary hypertension, and acute chest syndrome in women with SCD is associated with a SNP in the endothelial nitric oxide synthase gene (NOS3)." (PMID 23762099, 2013). "In particular, the NOS3 pathway induces pulmonary hypertension, oxidation stress of heart." (PMID 26538867, 2015). "However, other studies found increase in expression of NOS-3 in patients with pulmonary hypertension and in animal models of pulmonary hypertension." (PMID 16813666, 2006). "Therefore, we selected 16 single nucleotide polymorphisms in NOS3, DDAH1, DDAH2, AGXT2, ARG1, ARG2, and PRMT1 genes and studied their associations with dimethylarginine concentrations and the incidence of high-altitude pulmonary hypertension as well as acclimatization to high altitude." (PMID 34945057, 2021). "Biomarker genes for pulmonary hypertension included PRKG1, KCNMA1, FOXO1, and NOS3." (PMID 35740428, 2022).
ischemia (29 papers, 2010 to 2025). A hypoperfusion of the BLOOD through an organ or tissue caused by a PATHOLOGIC CONSTRICTION or obstruction of its BLOOD VESSELS, or an absence of BLOOD CIRCULATION. "As reported in a similar hypoxia-ischemia model, NOS3 is essential in the preservation and maintenance of microcirculation, inhibiting platelet aggregation, leukocyte adhesion, and migration and decreasing the inflammatory response." (PMID 30258527, 2018).
Sepsis (28 papers, 2010 to 2026). Sepsis is defined as life-threatening organ dysfunction caused by a dysregulated host response to infection. "An animal study highlighting the importance of the NOS3 gene demonstrated that NOS3-deficient mice experienced a greater degree of sepsis-associated MODS, with increased infiltration of mononuclear cells into tissues and heightened oxidative stress." (PMID 41226345, 2025). "The association between NOS3 gene polymorphisms and sepsis has been the subject of several studies, which suggested a potential role of these variants in modulating susceptibility to and severity of the disease; however, the results remain inconclusive." (PMID 41226345, 2025). "Recently, a study reported that the NOS3 T(-786)C rs2070744 genetic polymorphism was associated with susceptibility to develop sepsis among Turkish patients, potentially influencing the course of inflammation." (PMID 40142738, 2025). "A study conducted in Turkish patients who were followed up in the emergency department for sepsis has shown that the NOS3 T(-786)C genetic polymorphism might increase the susceptibility to sepsis." (PMID 40142738, 2025). "Moreover, it is the first to report the T allele of NOS3 c.-786T>C as a potential genetic risk factor for severe sepsis-related complications in this population." (PMID 41226345, 2025). "Furthermore, sepsis was associated with three NOS3 genetic polymorphisms, T(-786)C (rs2070744); 27-bp VNTR 4b/a (intron 4), and G894T (Glu298Asp, rs1799983)." (PMID 40142738, 2025). "Interestingly, NOS3 may functionally suppress sepsis‐caused systemic inflammation and myocardial dysfunction in mice." (PMID 33241658, 2021). "The analysis showed that NOS3, SIRT1, HSP90AA1, MMP9, MMP2, PTPRC, and TLR2 were associated with multiple organ damage in sepsis." (PMID 36406124, 2022). "The dysfunction of NO production in the microcirculation during sepsis is mediated by NOS3 dysfunction." (PMID 36406124, 2022). "A study on the role of NOS3 on myocardial performance indicated that NOS3 contributes to the bioactive NO pool during the development of sepsis and results in impaired cardiac contractility." (PMID 34765091, 2021). "On the other hand, the production of NO by NOS3, especially for the endothelial cell, is decreased during sepsis and prolonged endotoxemia." (PMID 25699985, 2015). "In conclusion, our results support that NOS3 is a major source of endogenous NO in developing sepsis leading to myocardial dysfunction." (PMID 23397596, 2013). "Our data suggest that NOS3 relevantly contributes to bioactive NO pool in developing sepsis resulting in impaired cardiac contractility." (PMID 23397596, 2013). "Given this controversy concerning a proinflammatory role of NOS3 and that NO is intricately involved in regulating cardiovascular function, the present study aims to elucidate the influence of NOS3 on myocardial function in sepsis development." (PMID 23397596, 2013). "When compared with baseline and NOS3−/− mice, mean arterial blood pressure was diminished in septic WT at 6 h after sepsis induction." (PMID 23397596, 2013). "We aimed to determine the role of NOS3 on myocardial performance, NO production, and time course of sepsis development." (PMID 23397596, 2013). "The main finding of the present study is that endothelial NOS (eNOS/NOS3) plays a key role in the development of sepsis." (PMID 23397596, 2013). "Fitting well with initial proinflammatory effects of NOS3, we observed that WT mice exhibited a more marked myocardial infiltration with neutrophils, monocytes, and lymphocytes in the hearts at 12 h after sepsis induction." (PMID 23397596, 2013). "Deviating from this pattern well known from several forms of human sepsis, septic NOS3−/− mice exhibited stable CO and preserved cardiac function." (PMID 23397596, 2013).
Sepsis (continued). "That NOS3 contributes to endogenous NO production in developing sepsis is supported by our finding that NOS3−/− mice exhibited a significantly smaller increase of plasma nitrate levels compared to WT during sepsis development." (PMID 23397596, 2013). "Unselective NOS inhibition with ethylthiourea (ETU) in NOS3−/− mice after sepsis induction diminished this survival benefit, with only a discreet improvement in survival time remaining (mean survival = 38 h, n = 12, p < 0.05)." (PMID 23397596, 2013). "The haplotype analysis further supported this finding, revealing that the T4bG haplotype of NOS3 polymorphisms was significantly more frequent among the patients who developed MODS, MOF, and sepsis, indicating a potential combined effect of these variants on susceptibility to severe complications." (PMID 41226345, 2025). "Among the three isoforms of NOS, NOS2 and NOS3 are more relevant to sepsis." (PMID 38029224, 2023). "Overexpression of cardiomyocyte-specific NOS3 protected patients from myocardial depression in sepsis, while endothelial NOS3 might impair cardiac contractility in developing sepsis." (PMID 38029224, 2023). "Indeed, experimental evidence indicates that inhibition of NOS1 and NOS3 activity during sepsis increases hepatic and splanchnic damage." (PMID 25699985, 2015). "It is known that increased nitrotyrosine formation during sepsis may uncouple NOS3 activity and increase oxidative stress." (PMID 23397596, 2013). "Myocardial NOS3 may have an important protective role against sepsis-induced myocardial dysfunction." (PMID 22482045, 2012). "Differential analysis of NOS3, MMP2, HSP90AA1, and SIRT1 in the sepsis kidney injury-control group (SKi-C) showed that the p-value were all <0.05, indicating differential expression." (PMID 36406124, 2022). "During inflammation and sepsis, this NOS1 and NOS3-mediated NO production is reduced, reducing blood flow to the individual organs, thereby compromising its function." (PMID 25699985, 2015). "Supplementation of the non-selective NOS inhibitor l-NAME in an experimental hyperdynamic sepsis model in ewes lead to a normalized renal blood flow, indicating an important contribution of the local NOS1 and NOS3 derived NO production in the hypotension." (PMID 25699985, 2015). "With a large amount of data supporting a detrimental role for NOS2 in sepsis, it might be expected that NOS2 inhibition would result in additional survival benefit in NOS3−/− mice." (PMID 23397596, 2013). "Susceptibility to NOS3 stimulation by bradykinin was approximately twice as pronounced in WT CLP mice as compared to non-septic mice, indicating a high level of NOS3 activation secondary to sepsis." (PMID 23397596, 2013). "Therefore, it is suggested that the upregulation of NOS2 during sepsis may compensate for the downregulation of NOS1 and NOS3 with respect to organ perfusion." (PMID 25699985, 2015).